DHODH (dihydroorotate dehydrogenase (quinone))
Diseases named in the same sentence as DHODH in open-access papers (continued):
Sharing a sentence is not in itself a finding about the gene and the disease.
tumor (108 papers, 2008 to 2026). "CIRT treatment significantly reduced tumor volume, tumor weight, and DHODH expression, while also modulating the expression of ferroptosis-related markers and macrophage polarization-associated factors in tumor tissues." (PMID 40917841, 2025). "As expected, DHODH inhibition significantly suppressed tumor growth and reduced Ki-67-positive cells in NF2-deficient tumors, while having minimal effects on wild-type tumors." (PMID 40707702, 2025). "Dihydroorotate dehydrogenase (DHODH), a key enzyme implicated in cancer progression, has been linked to tumor radiosensitivity." (PMID 40917841, 2025). "The TIMER 2.0 online tool was used to explore the mutation status of DHODH in different tumors and its effect on the prognosis of each tumor." (PMID 38796629, 2024). "Within public datasets, increased DHODH expression was identified in group 3 and shh MB tumours and was associated with poor survival in group 3." (PMID 39766063, 2024). "Inhibition of both tumor-specific driver mutations and DHODH activity demonstrated sustained inhibition of pyrimidine synthesis and tumorigenic capacity." (PMID 37298093, 2023). "Our in silico result from the TCGA dataset demonstrates that DHODH overexpression in hypoxic tumor environments is associated with high levels of genomic instability." (PMID 38136273, 2023). "For example, dihydroorotate dehydrogenase (DHODH) in mitochondria can reduce the damage caused by reactive oxygen species to tumor cell mitochondria." (PMID 38312507, 2023). "Our in silico data analysis suggests that the co-occurrence of DHODH overexpression and mutated DNA replicative polymerases can contribute toward unfavorable outcomes in high-grade tumor cases." (PMID 38136273, 2023). "In the mouse tumour model, pyrimidine biosynthesis, which is dependent on respiration-linked dihydroorotate dehydrogenase (DHODH), is essential for tumour growth, while the production of ATP by ATP synthase is dispensable for tumorigenesis." (PMID 31052256, 2019). "Moreover, DHODH has been implicated in regulating macropinocytosis, supporting nutrient scavenging in nutrient-limited tumor microenvironments and indirectly shaping the immune landscape." (PMID 41369379, 2025). "Beyond its canonical metabolic function, DHODH has also been implicated in tumor–immune crosstalk." (PMID 41239499, 2025). "DHODH inhibition in this context can cause nucleotide pool imbalance, leading to tumor suppression." (PMID 40961924, 2025). "Further, DHODH inhibition resulted in the induction of senescence, and the associated increase of pro-inflammatory cytokines, in tumor cells." (PMID 32034120, 2020). "DHODH inhibition drives tumor differentiation and suppresses proliferation in cSCC, highlighting metabolic dependency as a potential therapeutic vulnerability." (PMID 42049699, 2026). "Intriguingly, dynamic equilibrium exists between mGPX4 and DHODH pathways: tumor cells counteract LPO induced by DHODH inhibition through mGPX4 upregulation, whereas cytosolic GPX4 lacks such compensatory capacity." (PMID 40919133, 2025). "The results demonstrated that suppression of DHODH expression significantly lowered the tumor immune dysfunction and exclusion (TIDE) score, implying a weakened response to ICB therapy." (PMID 41239499, 2025). "DHODH inhibitors are emerging as promising candidates for treating proliferative disorders, including cancers, by stopping tumor cell proliferation in various contexts." (PMID 40284407, 2025). "From a translational perspective, DHODH inhibition represents a dual-action strategy: directly sensitizing tumor cells to ferroptosis and indirectly enhancing immune surveillance." (PMID 41369379, 2025). "Inhibition of PDE7A attenuates de novo pyrimidine biosynthesis by repressing DHODH expression, causing suppression of TNBC tumor growth and metastasis." (PMID 40961924, 2025). "Inactivation of DHODH enhances T cell infiltration and potentiates the efficacy of PD-1 checkpoint blockade in mouse tumor models." (PMID 41369379, 2025).
tumor (continued). "To explore this, we rationally designed and synthesized a tumor-selective prodrug, H62, by conjugating our potent DHODH inhibitor EA6 with the validated STING agonist MSA-2 (MSA) via a cathepsin B (CTSB)-cleavable linker." (PMID 41239499, 2025). "Recent studies have expanded the role of DHODH beyond intrinsic tumor metabolism to include modulation of the tumor microenvironment and immune evasion." (PMID 41369379, 2025). "CIRT treatment decreased the tumor volume and weight as compared to the control group (p < 0.01), while DHODH overexpression increased the tumor volume and weight in comparison to the CIRT group (p < 0.05)." (PMID 40917841, 2025). "The mitochondria-localized enzyme DHODH has emerged as a central regulator in this context, influencing both cancer cell-intrinsic ferroptosis defenses and the composition of the tumor immune microenvironment." (PMID 41369379, 2025). "Nonetheless, its involvement in tumor growth has made DHODH an attractive therapeutic target, prompting the development of various DHODH inhibitors." (PMID 40513779, 2025). "To overcome this limitation, we designed H62, a tumor-selective prodrug conjugating the DHODH inhibitor EA6 with the STING agonist MSA-2 via a cathepsin B-cleavable linker." (PMID 41239499, 2025). "Over the past decades, advances in understanding pyrimidine metabolism and its inhibitors, such as dihydroorotate dehydrogenase (DHODH) blockers, have revealed their dual role in tumor suppression and immune modulation." (PMID 41463008, 2025). "To validate that the antitumor activity of H62 is mediated by inhibiting DHODH, we knocked down DHODH expression in A375 and B16F10 cells to confirm the crucial role of DHODH in H62-induced tumor cell death." (PMID 41239499, 2025). "In vivo, CIRT significantly reduced tumor growth in xenograft models, and this effect was attenuated by DHODH overexpression." (PMID 40917841, 2025). "The specificity of enhanced sensitivity to BCL-XL targeting conferred by DHODH inhibition in PDAC appears be ingrained in PDAC tumor physiology at baseline." (PMID 40738904, 2025). "To overcome resistance and enhance antitumor immunity, we rationally engineered the tumor-activated prodrug H62, which combines a potent DHODH inhibitor (EA6) with a validated STING agonist (MSA) via a protease-cleavable linker." (PMID 41239499, 2025). "In summary, DHODH is more than a mitochondrial enzyme in pyrimidine synthesis–it is a metabolic checkpoint that links ferroptosis regulation with tumor immunity." (PMID 41369379, 2025). "BAY-2402234 and other DHODH inhibitors are currently being evaluated in clinical trials, with a focus on its ability to trigger cell differentiation and halt tumor growth, particularly myeloid malignancies." (PMID 40961924, 2025). "The inhibition of DHODH in NB models via brequinar significantly curtails tumor growth and prolongs survival." (PMID 39964621, 2025). "Conversely, DHODH inhibition amplifies ferroptosis and enhances immune recognition of tumor cells, supporting its potential use as an immunotherapy adjuvant." (PMID 41369379, 2025). "Recent work has shown that DHODH sustains tumor macropinocytosis through O-GlcNAcylation of neuropilin-1 (NRP1), which promotes nutrient scavenging and suppresses MHC class II expression on tumor cells." (PMID 41369379, 2025). "The expression of DHODH in tumor tissues was downregulated by CIRT (p < 0.001), which was reversed by DHODH overexpression (p < 0.001)." (PMID 40917841, 2025). "Future studies will include such a group to further delineate the mechanistic role of DHODH in the tumor microenvironment." (PMID 40917841, 2025). "Another limitation of our study is the absence of an in vivo group with DHODH overexpression alone (without CIRT), which would help to clarify the independent contribution of DHODH to tumor progression and immune modulation." (PMID 40917841, 2025).
tumor (continued). "Tumor volume analysis revealed that uridine supplementation significantly abrogated the tumor-suppressive effect of H62, indicating that DHODH inhibition is a critical component of H62’s efficacy." (PMID 41239499, 2025). "In vivo, DHODH inhibitors (e.g., brequinar) reduce tumor burden and prolong survival at tolerable dosing schedules, suggesting a therapeutic window." (PMID 41295305, 2025). "For example, in breast and lung cancer models, dual targeting of DHODH and PD-1/PD-L1 pathways significantly improved tumor control compared to either therapy alone." (PMID 41369379, 2025). "H62 effectively triggered tumor pyroptosis and NK cell recruitment via DHODH inhibition, while concurrently activating NK cells through STING signaling." (PMID 41239499, 2025). "We then examine the diverse contributions of DHODH to tumor progression, therapy resistance, and immune evasion." (PMID 41369379, 2025). "In a mouse xenograft model also, ectopic expression of DHODH in PDE7A-KO TNBC cells rescued their tumor growth." (PMID 40961924, 2025). "Studies have shown that DHODH plays a minor role in tumor cell ferroptosis, which questions its role as a ferroptosis-regulating protein and supports our findings." (PMID 39737072, 2024). "As cell proliferation and migration are critical phenotypes for tumor progression, we examined the effects of DHODH gene knockdown on ccRCC cells in vitro." (PMID 38796629, 2024). "Manganese (Mn2+) enhances cGAS-STING signaling, downregulating dihydroorotate dehydrogenase (DHODH), an enzyme that regulates mtROS production and lipid peroxidation, promoting ferroptosis in murine tumor cells." (PMID 39595619, 2024). "The potential regulatory role of DHODH in the cell cycle, ferroptosis, and resistance of different tumor cells is also crucial." (PMID 38796629, 2024). "Metabolomics analysis of BQ- and vehicle-treated tumors separated in principal component analysis and unsupervised hierarchical clustering, confirming the perturbation of tumor metabolism following DHODH inhibition." (PMID 37066260, 2024). "Inactivation of DHODH can induce mitochondrial lipid peroxidation with reduced expression of GPX4 in tumor cells, leading to the occurrence of ferroptosis." (PMID 38481532, 2024). "DHODH was found to be mainly present in arm-level deletions and was diploid in multiple tumor types." (PMID 38796629, 2024). "Our results demonstrate that by inhibiting DHODH with brequinar, tumour cell growth and MYC levels are significantly reduced." (PMID 39766063, 2024). "In our study, we reveal the interplay of MYC and DHODH in group 3 MB, based on the group-specific expression of DHODH in MB tumours, and discover the sustained inhibition of MYC expression upon BRQ single-dose treatment in two human MB cell lines." (PMID 39766063, 2024). "For example, DHODH-dependent respiration has been shown to be important for tumor formation but has little effect on ATP synthesis rates." (PMID 37358264, 2023). "Consistent with this phenotype, lower accumulation of DHODH and higher lipid peroxidation under Oxaliplatin treatment were observed in the PDX tumor expressing lower levels of both pLOXL3-S704 and DHODH." (PMID 37253718, 2023). "Our data show that DHODH overexpression with a DNA replicative polymerase (POLE and POLD1) mutation is significantly associated with high-grade (Grade III) tumor status." (PMID 38136273, 2023). "For example, dihydroartemisinin (DAT) combined with RSL3, the HDAC inhibitor vorinostat combined with Erastin, and the DHODH inhibitor brequinar combined with sulfapyridine all induce ferroptosis in tumor cells." (PMID 36672372, 2023).
tumor (continued). "To precisely calculate the correlation between AK2, LOXL3-S704 phosphorylation, and DHODH, we stained the tumor tissues of the 60 HCC patients using antibodies against AK2 while pLOXL3-S704 and DHODH were measured previously." (PMID 37253718, 2023). "Zhang et.al reported that DHODH inhibition alone was sufficient to induce lipid peroxidation and ferroptosis in tumor cells." (PMID 37580393, 2023). "The nude mouse xenograft model was generated to examine the effect of combination of DHODH inhibition and cisplatin on tumor growth in vivo." (PMID 36672495, 2023). "As several oncogenic backgrounds share synthetic lethality with DHODH, it will be important to select tumor types that are highly sensitive to DHODH inhibitors and to combine molecularly targeted drugs with DHODH inhibitors." (PMID 37744270, 2023). "Previously, we have shown that emvododstat (PTC299) does not inhibit murine DHODH, and consequently, any effect of the drug on DHO levels and tumor growth would be a direct effect of emvododstat on the human DHODH in the xenograft itself." (PMID 35223511, 2022). "It has recently been demonstrated that GPX4 activity is mediated by DHODH and that brequinar suppresses tumor growth of GPX4lo cells by inducing ferroptosis." (PMID 35943801, 2022). "The inhibition of tumor growth by emvododstat was more prolonged at 10 mg/kg compared with 3 mg/kg despite both doses resulting in the inhibition of DHODH as shown by the increased levels of DHO." (PMID 35223511, 2022). "In these studies, blockade of this pathway by various means, including the DHODH inhibitor leflunomide, attenuates cell growth and tumour progression, suggesting a critical dependence on DHODH specifically in MEN1-mutated tissue." (PMID 36694894, 2022). "DHODH, a key enzyme in the de novo biosynthesis of pyrimidine nucleotides, has appeared as a therapeutic target for a variety of tumor treatments." (PMID 36524129, 2022). "DHODH not only plays a vital part in malignancy therapy, but also in many other non-neoplastic diseases." (PMID 33971967, 2021). "A recent study demonstrates that the sensitivity of SCLC cells toward disruption of the pyrimidine biosynthesis pathway enhanced, and DHODH inhibition by BRQ suppresses SCLC tumor growth and extends mice survival in vivo." (PMID 33971967, 2021). "DHODH inhibition by leflunomide also strongly impairs CRC liver metastatic colonization compared with primary tumor growth." (PMID 33971967, 2021). "Results indicate significantly DHODH shows higher activity in malignant tumor tissue than in adjacent normal tissue." (PMID 33971967, 2021). "Collectively, DHODH, revealing multiple biological functions in neoplastic and non-neoplastic diseases, has broad-spectrum prospective remained to be explored." (PMID 33971967, 2021). "This suggests that inhibition of DHODH specifically impairs the production of pyrimidines in tumor tissues with low side effects." (PMID 33201894, 2020). "Our results indicate that chronic inhibition of DHODH by leflunomide (LFN) blocks UVB-induced tumor initiation." (PMID 31551419, 2019). "In cells with defective cell-cycle checkpoints, like many tumours, DHODH inhibition led to the accumulation of cells in S-phase and this associated with a lowering of levels of cdc6, a key factor involved in licencing of origins of replication." (PMID 30689917, 2019). "DHODH activity was apparently higher in cultured HeLa cells than in fibroblasts, and also significantly higher in malignant tumour tissue than in adjacent normal tissue." (PMID 28084471, 2017). "Deletion of DHODH in a panel of tumor cells completely blocked or delayed tumor growth." (PMID 41248423, 2026).
tumor (continued). "Intriguingly, a recent study revealed that DHODH-mediated pyrimidine synthesis plays a role in suppressing mitochondrial lipid peroxidation and ferroptosis, suggesting it may contribute to tumor survival through an additional defense mechanism." (PMID 40707702, 2025). "Moreover, DHODH expression is frequently upregulated in a wide range of malignancies and is strongly correlated with tumor aggressiveness, metastasis, and poor prognosis." (PMID 41369379, 2025). "Pharmacological co-targeting of PDE7A and DHODH potently inhibits TNBC tumor growth and metastasis." (PMID 40961924, 2025). "Moreover, tumor metabolic plasticity, through pathways like transsulfuration or DHODH‐mediated ubiquinol synthesis, highlights the need for next‐generation FINs with orthogonal targeting mechanisms." (PMID 40919133, 2025). "Furthermore, studies indicate that DHODH regulates not only tumor intrinsic metabolic survival programs but also shapes the tumor immune microenvironment by modulating antigen presentation, lipid remodeling, and T cell cytotoxicity." (PMID 41369379, 2025). "Since the identification of dihydroorotate dehydrogenase (DHODH) as a mitochondrial suppressor of ferroptosis in 2021, increasing evidence has highlighted its role in linking nucleotide metabolism, redox regulation, and tumor progression." (PMID 41369379, 2025). "Therefore, targeting de novo pyrimidine synthesis with DHODH inhibitors disrupts the metabolic and biosynthetic processes, leading to the cytotoxic effects observed in tumor cells reliant on this pathway for survival." (PMID 40284407, 2025). "Additionally, western blotting validates the expression of FTH1, GPX4, SLC7A11, FSP1 and DHODH in fresh surgical tumour tissues from three imatinib‐resistant patients compared with three imatinib‐sensitive patients receiving neoadjuvant imatinib therapy." (PMID 40866937, 2025). "Furthermore, pharmacological targeting of DHODH reverses PD-1 resistance by disrupting tumor macropinocytosis and restoring antigen presentation." (PMID 41369379, 2025). "DHODH inhibitors have been demonstrated in multiple trials to effectively destroy tumour cells." (PMID 41126320, 2025). "Histologically, LEF decreased DHODH expression and tumor vascularization." (PMID 39815040, 2025). "Next, we examined whether DHODH inhibition exerts similar tumor-suppressive effects on TNBC cells as those observed in response to PDE7A inhibition." (PMID 40961924, 2025). "In addition, DHODH-mediated ferroptosis defense has been shown to shape the tumor immune microenvironment by modulating lipid peroxidation, antigen presentation, and T cell infiltration." (PMID 41369379, 2025). "However, when GPX4 is highly expressed, combining ferroptosis inducers with DHODH inhibitors significantly increases ferroptosis levels in tumor cells." (PMID 39065721, 2024). "DHODH inhibitors can block tumor growth by inducing ferroptosis." (PMID 38796629, 2024). "The application of the DHODH inhibitor brequinar inhibited the growth of tumor cells with low GPX4 expression in vitro, and the combined treatment of brequinar and the SLC7A11 inhibitor sulfasalazine abolished the growth of tumor cells with high GPX4 expression." (PMID 38562175, 2024). "However, inhibiting the pyrimidine biosynthesis pathway mediated by CAD and DHODH through drug intervention can render tumor cells sensitive to chemotherapy." (PMID 38796629, 2024). "Manganese activates cGAS-STING to promote mitochondrial lipid peroxidation and ROS production by releasing type I IFN to reduce DHODH function, thereby inducing ferroptosis in tumour, providing a new strategy to complement existing anti-tumour treatment options." (PMID 39183465, 2024). "Interestingly, 72% and 73% of endometrial tumors with DHODH overexpression co-occurrence with a POLE and POLD1 mutation are significantly associated with high-grade tumor stages, respectively (** p < 0.01, **** p < 0.0001)." (PMID 38136273, 2023).